RN7SL45P (RNA, 7SL, cytoplasmic 45, pseudogene)
Gene: Miscellaneous RNA gene on chromosome 17 (31,518,432 to 31,518,729, forward strand). Ensembl gene ENSG00000264862.
Homologues: Orthologues: macaque Metazoa_SRP (93% identical). Paralogues in human: RN7SL1 (89% identical), RN7SL2 (88% identical), RN7SL3 (87% identical), RN7SL126P (86% identical), RN7SL769P (85% identical), RN7SL230P (85% identical), RN7SL665P (84% identical), RN7SL186P (84% identical), RN7SL7P (84% identical), RN7SL326P (84% identical), RN7SL386P (84% identical), RN7SL322P (83% identical), and 705 more.